LONP1 (lon peptidase 1, mitochondrial)
Diseases named in the same sentence as LONP1 in open-access papers (continued):
Sharing a sentence is not in itself a finding about the gene and the disease.
renal fibrosis (7 papers, 2023 to 2025). A final common manifestation of a wide variety of chronic kidney diseases characterized by glomerulosclerosis and tubulointerstitial fibrosis. "Further animal studies using adeno‐associated virus (AAV)‐Ksp‐LONP‐overexpressing accelerated aged mouse models revealed the regulatory role of LONP1 in age‐associated renal mitochondrial dysfunction and renal fibrosis." (PMID 39261902, 2024). "Lon protease 1 (LONP1) has been reported to be responsible for ageing‐related renal fibrosis; however, the underlying mechanism(s) of LONP1‐driven kidney ageing with respect to mitochondrial disturbances remains to be further explored." (PMID 39261902, 2024). "In the present study, we initially posited that ageing‐related renal fibrosis is linked to decreased LONP1 levels." (PMID 39261902, 2024). "Notably, SOD2 supplementation (application of SOD2 mimetics or exogenous transfection of SOD2 plasmid) effectively alleviated endothelial injury and renal fibrosis exacerbated by LONP1 deficiency." (PMID 41275592, 2025). "After showing that HMGCS2 is a possible substrate of LONP1, the authors explored the therapeutic potential of 84-B10 as a LONP1 activator, targeting its role in renal fibrosis and tubular epithelial cell protection." (PMID 40305312, 2025). "In summary, our research indicates that LONP1 contributes to ageing‐related renal fibrosis by modulating mitochondrial homeostasis." (PMID 39261902, 2024). "Future research will incorporate data from naturally aged mice and human renal samples to enhance understanding of LONP1's role in renal fibrosis." (PMID 39261902, 2024). "In our study, the results revealed that the expression of LONP1 was decreased in kidney biopsy samples from aged people compared to those from younger people, demonstrating a crucial role for LONP1 in renal fibrosis during ageing." (PMID 39261902, 2024). "Effects of LONP1 silencing or overexpression on renal fibrosis and mitochondrial quality control were explored." (PMID 39261902, 2024). "LONP1 deletion significantly accelerated ageing‐related renal fibrosis and mitochondrial dysfunction in HK‐2 cells, while LONP1 overexpression had the opposite effect." (PMID 39261902, 2024). "The results indicated that kidney ageing was accompanied by mitochondrial dysfunction and increased renal fibrosis with downregulated LONP1." (PMID 39261902, 2024). "One study highlighted an LONP1 activator, 84-B10, which has shown mitochondrial protective effects and antagonistic effects on renal fibrosis in mice." (PMID 38625722, 2024). "Overexpression of LONP1 alleviated renal fibrosis and maintained mitochondrial homeostasis, while silencing of LONP1 had the opposite effect." (PMID 39261902, 2024). "LONP1 expression was reduced in the kidneys of aged humans and mice, accompanied by renal fibrosis and mitochondrial dysregulation." (PMID 39261902, 2024). "Our data showed that the overexpression of LONP1 mitigated ageing‐related renal fibrosis and mitochondrial dysfunction." (PMID 39261902, 2024). "Exploring the regulation of LONP1 as a novel research focus highlights its crucial role in maintaining mitochondrial homeostasis and delaying renal fibrosis." (PMID 39261902, 2024). "On the basis of the specific interaction between METTL3 and LONP1, the ablation of METTL3 simultaneously reduced the methylation and protein levels of LONP1, accelerating renal fibrosis by maintaining mitochondrial homeostasis." (PMID 39261902, 2024). "LONP1 was reported to play a protective role against the progression of renal fibrosis in two CKD models (unilateral ureteral obstruction and 5/6 nephrectomy) by preserving mitochondrial homeostasis." (PMID 39261902, 2024). "Together, these data indicate that tubule‐specific overexpression or deletion of Lonp1 alleviated or aggravated UUO‐induced renal fibrosis and mitochondrial dysfunction." (PMID 36629048, 2023).
renal fibrosis (continued). "84-B10 was identified as a new LonP1 activator and has been proved to attenuate renal fibrosis and mitochondrial dysfunction." (PMID 38202741, 2023). "By using renal tubular Lonp1‐cKO or Lonp1‐cKI mice and proximal tubular epithelial cells, we demonstrated for the first time that LONP1 prevents the progression of renal fibrosis in two CKD models (UUO and 5/6Nx) by maintaining mitochondrial homeostasis." (PMID 36629048, 2023). "Here, we found Lonp1 deletion impaired mitochondrial homeostasis and aggravated renal fibrosis through HMGCS2 accumulation in CKD mice or cellular models, whereas Lonp1 overexpression or treatment with an LONP1 activator alleviated these injuries." (PMID 36629048, 2023). "Overall, our results suggest that LONP1, to the best of our knowledge, acts as an important factor in the renal fibrosis of CKD by degrading HMGCS2 and thereby regulating mitochondrial homeostasis." (PMID 36629048, 2023). "Collectively, these results demonstrate that LONP1 attenuated mitochondrial dysfunction and renal fibrosis, possibly by degrading HMGCS2 to prevent the accumulation of HMGCS2 under CKD conditions." (PMID 36629048, 2023). "Our previous studies showed that LONP1 expression in kidney tissues of CKD patients was significantly reduced, and its absence in podocytes caused podocytopathy, and in tubular epithelial cells led to mitochondrial dysfunction and renal fibrosis." (PMID 41275592, 2025). "Furthermore, we overexpressed LONP1 in mice treated with D‐gal and then measured the degree of renal fibrosis and mitochondrial function." (PMID 39261902, 2024). "Furthermore, for the first time, we revealed that LONP1 impeded the progression of renal fibrosis by alleviating mitochondrial dysfunction in D‐gal‐treated mice and cells after transfection with AAV‐Ksp‐shLONP1 or AAV‐Ksp‐LONP1." (PMID 39261902, 2024). "LONP1 mediates mitochondrial function in kidney ageing and that targeting LONP1 may be a potential therapeutic strategy for improving ageing‐related renal fibrosis." (PMID 39261902, 2024). "Theoretically, some of these factors may also participate in the renal fibrosis of CKD by regulating LONP1." (PMID 36629048, 2023). "Pharmacologically, the LONP1 activator attenuated renal fibrosis and mitochondrial dysfunction." (PMID 36629048, 2023). "Based on these findings, we hypothesized the decreased LONP1 expression in renal tubules might mediate renal fibrosis in CKD." (PMID 36629048, 2023). "Moreover, the LONP1‐expression level correlated negatively with the degree of kidney fibrosis, suggesting a key role for LONP1 in renal fibrosis." (PMID 36629048, 2023). "We validated these results by demonstrating that the pharmacological activator of LONP1 could attenuate renal fibrosis and mitochondrial function." (PMID 36629048, 2023). "Furthermore, the decreased LONP1 in renal tubules may be responsible for the progression of renal fibrosis in CKD patients." (PMID 39261902, 2024). "Moreover, we explored whether the functional role of METTL3 in mitochondrial dysfunction and renal fibrosis occurs through the m6A modification of LONP1." (PMID 39261902, 2024). "In this study, we observed a prominent decrease in LONP1 expression (mainly renal tubular LONP1 expression) in kidney biopsy tissues from patients with CKD, compared with the expression levels in control kidney tissues, with varying degrees of renal fibrosis." (PMID 36629048, 2023). "Activation of the mitochondrial protease Lon protease 1 (LONP1) attenuates mitochondrial dysfunction and renal fibrosis in chronic kidney disease (CKD) mice, suggesting that targeting LONP1 might represent a novel therapeutic strategy for CKD." (PMID 36629048, 2023). "These reported substrates were not differentially expressed based on our proteomics data (Fig EV4A), but this does not rule out whether they play roles in LONP1 dysfunction in renal fibrosis, which requires further investigation." (PMID 36629048, 2023).
renal fibrosis (continued). "LonP1 was identified as an endogenous mitochondrial regulator in renal tubular cells under CKD conditions and its deletion could impair mitochondrial homeostasis and aggravated renal fibrosis through the substrate accumulation." (PMID 38202741, 2023). "However, no reports have demonstrated the involvement of LONP1 in renal fibrosis." (PMID 36629048, 2023).
colon carcinoma (6 papers, 2018 to 2026). "As LONP1 downregulation is associated with altered functionality and morphology of colon cancer cells in vitro and with lower risk of developing colon cancer in mice, we decided to analyze possible differences present in the colon." (PMID 32521756, 2020). "We previously demonstrated that LonP1 silencing is associated with severe mitochondrial dysfunction and apoptosis susceptibility in colon cancer cell lines." (PMID 30038898, 2018). "Since LONP1 depletion has been associated with lower risk of developing colon cancer in mice, and since its downregulation deeply alters morphology and functionality of colon cancer cells in vitro, we decided to focus our attention on possible differences present in colon." (PMID 32521756, 2020). "In line with our data on breast cancer cells, Lonp1 downregulation suppressed cervical cancer cell proliferation and induced cell death in colon cancer cells." (PMID 36313646, 2022). "Among them was Lon protease 1 (Lonp1), being important in cervical cancer and colon cancer cells, as discussed further below." (PMID 36313646, 2022). "We reported that LonP1 modulation led to important changes in total β-ctn levels, in several colon cancer cell lines." (PMID 30038898, 2018). "We found that silencing LonP1 leads to severe mitochondrial impairment and apoptosis in colon cancer cells." (PMID 30038898, 2018). "In this study, we analyzed the expression of LonP1 in different stages of colon cancer and the consequences of its upregulation at the mitochondrial and cellular level." (PMID 30038898, 2018). "We found that in colon cancer cells LonP1 can influence glycolytic activity together with mitochondrial activity." (PMID 30038898, 2018). "Interestingly, tumor tissue expressed more LONP1 protein compared to its counterpart in patient with colon cancer." (PMID 36739437, 2023). "We have previously shown that LONP1 downregulation determines a severe impairment of mitochondrial morphology and functionality in colon cancer cells, and that this impacts on epithelial mesenchymal transition in colon cancer." (PMID 32521756, 2020). "In this study, we show that elevated expression of LonP1 in CRC tissues is associated with nuclear localization of β-ctn, and that overexpression of LonP1, in vitro, differently affects β-ctn expression in SW480 and SW620 colon cancer cells." (PMID 30038898, 2018). "LonP1 upregulation also induced opposite changes in oxidative phosphorylation, glycolysis, and pentose pathway in SW480 primary colon tumor cells when compared to SW620 metastatic colon cancer cells." (PMID 30038898, 2018). "Here, we investigate the role of LonP1 in mitochondrial functions, metabolism, and epithelial–mesenchymal transition (EMT) in colon tumor cells and in metastasis." (PMID 30038898, 2018). "Importantly, LonP1 is virtually absent in normal mucosa, gradually increasing from aberrant crypt foci to adenomas, with the highest expression level in colon cancer." (PMID 39179991, 2024). "However, the precise role of LonP1 in colon cancer progression has not been clarified." (PMID 30038898, 2018).
prostate carcinoma (6 papers, 2016 to 2026). A carcinoma that arises from epithelial cells of the prostate gland. "Lon Peptidase 1(LONP1) is closely associated with mitochondrial homeostasis and prostate cancer progression." (PMID 41556186, 2026). "Consistently, prostate cancer patients with high levels of both LONP1 and ClpP expression showed significantly worse survival outcomes than those with only high LONP1 or ClpP expression." (PMID 33637676, 2021). "RNA expression of both LONP1 and ClpP were significantly upregulated in a wide range of human cancers, including bladder, breast, colon, kidney, lung, thyroid, uterine, and prostate cancer, compared with normal tissue." (PMID 33637676, 2021). "Separate knockdown of LONP1 or ClpP genes with small interfering RNA (siRNA) reduced the growth of prostate cancer cells, including LNCaP, C4-2B, DU145, and PC3 cells." (PMID 33637676, 2021). "Interestingly, LONP1 and ClpP genes closely localized to chromosomal region 19 (19q13), and the genomic locus of these two genes frequently exhibited gain in prostate cancer patient samples." (PMID 33637676, 2021). "In addition, in the Cancer Cell Line Encyclopedia (CCLE) database containing 1457 cancer cell lines, median ClpP expression was the highest in prostate cancer, and LONP1 expression was also highly elevated in prostate cancer relative to other cancer types." (PMID 33637676, 2021). "Additionally, prostate cancer patients with higher LONP1 and ClpP expression exhibited poorer survival." (PMID 33637676, 2021). "To assess whether co-expression of these two proteases plays a role in cancer, we examined whether LONP1 and ClpP downregulation jointly impact the proliferation of prostate cancer cells." (PMID 33637676, 2021). "In agreement with mRNA data, LONP1 and ClpP proteins were highly co-expressed in prostate cancer compared with non-transformed prostate cells, including RWPE1 and BPH1 cells." (PMID 33637676, 2021). "For comparison, another protease involved in mitochondrial protein quality control, LonP1, was expressed in normal prostate but not prostate cancer." (PMID 27389535, 2016).
multiple myeloma (5 papers, 2021 to 2025). "In this study, we provide evidence that the mitochondrial matrix protease LonP1 causes partial resistance to proteasome inhibition in multiple myeloma." (PMID 33671345, 2021). "LONP1 is an interesting target to consider as it is essential for cell survival and has emerged as a putative target for cancer therapy, and has also been implicated in resistance to PIs in myeloma." (PMID 37149844, 2023). "BTZ, a clinically used proteasome inhibitor for multiple myeloma treatment, has been reported to inhibit LONP1 protease activity." (PMID 40332105, 2025). "It certainly makes the ancient LonP1 protease, an enzyme that is conserved in all kingdoms of life, a promising new target for the treatment of multiple myeloma." (PMID 33671345, 2021). "High expression of LONP1 and OSGEPL1 (O-sialoglycoprotein endopeptidase-like protein 1) in multiple myeloma cells were both associated with more aggressive outcomes and a 1.9- and 1.8-fold shorter median survival, respectively." (PMID 33671345, 2021). "The acute cytotoxicities of bortezomib and carfilzomib were significantly reduced by 10% and by 25%, respectively, when myeloma cells overexpressed LonP1." (PMID 33671345, 2021). "In this study, we provide evidence that the mitochondrial protease LonP1 can compensate when the proteasome is inhibited and that increased levels of LonP1 confer partial resistance against proteasome inhibitors in multiple myeloma." (PMID 33671345, 2021). "To better understand the transcriptional networks in which LONP1 and OSGEPL1 function, we analyzed the genome-wide co-expression relationships of these two genes in multiple myeloma cells of 747 patients." (PMID 33671345, 2021). "Furthermore, LonP1 showed up to 15-fold differences in expression levels among primary multiple myeloma samples, indicating that this mitoprotease might contribute to clinically relevant resistance mechanisms or the emergence of relapsed/refractory multiple myeloma." (PMID 33671345, 2021). "The fact that multiple myeloma cells treated with carfilzomib showed increased LONP1 expression indicates that the up-regulation of this mitoprotease is a result of proteasome inhibition, and not in response to LonP1 inhibition." (PMID 33671345, 2021).
dilated cardiomyopathy (4 papers, 2021 to 2025). Cardiomyopathy which is characterized by dilation and contractile dysfunction of the left and right ventricles. "Furthermore, loss of the mitochondrial matrix protease LonP1 significantly inhibits MAM formation, resulting in mitochondrial fragmentation and HF related to dilated cardiomyopathy." (PMID 40804395, 2025).
heart failure (4 papers, 2020 to 2024). Inability of the heart to pump blood at an adequate rate to meet tissue metabolic requirements. "Murine embryos with LonP1-deficient myocardial tissue show abnormal myocardial development, heart failure, and death at birth." (PMID 36362158, 2022). "Finally, our results show that LonP1 deficiency in the heart results in aberrant metabolic reprogramming and pathological heart remodeling and eventually progresses to heart failure." (PMID 37333972, 2023). "Moreover, a deficiency in LonP1 within the heart triggers metabolic reprogramming in cardiomyocytes, significantly upregulating genes associated with gluconeogenesis and amino acid metabolism, contributing to pathological heart failure." (PMID 38374992, 2024). "Targeting LonP1 presents a promising therapeutic approach for the treatment of heart failure." (PMID 38374992, 2024). "However, murine hearts with a deletion of LonP1 still maintain high glycolytic activity at E12.5, and myocardial development is impaired until the mice die of heart failure at birth." (PMID 36362158, 2022). "In conclusion, the cardiomyocyte-specific deletion of LonP1 leads to DCM and heart failure, which reveals that LonP1 is indispensable for heart function." (PMID 37333972, 2023). "As the reduction of LonP1 protein in cardiac myocytes leads to DCM and heart failure, it is possible that increased expression of LonP1 may have a cardioprotective effect against DCM, preventing heart failure." (PMID 37333972, 2023). "Later on, expression of LONP1 and HTRA2 was increased in mutant hearts, likely as a compensatory mechanism but still could not prevent mutant hearts from developing chamber dilation and heart failure in the end." (PMID 31209364, 2020).
atherosclerosis (3 papers, 2022 to 2023). A disease characterized by the build-up of fatty material and calcium deposition in the arterial wall resulting in partial or complete occlusion of the arterial lumen. "The development of allosteric inhibitors and activators of LonP1 will be invaluable in elucidating its mechanistic and functional complexities and holds promise for chemotherapeutic benefit in treating cancers and age-associated disorders such as atherosclerosis and neurodegeneration." (PMID 35151690, 2022). "The mitochondrial matrix protein LONP1 has been shown to be involved in atherosclerosis mitochondrial protein quality control and is a strong risk factor of relapse." (PMID 37199828, 2023). "During atherosclerosis, Lonp1 is upregulated in macrophages by saturated fatty acids and by PERK-eIF2α activated signaling." (PMID 36978846, 2023). "Studies in mouse models have also shown the involvement of Lonp1 in atherosclerosis, and its oxidative inactivation after transaortic constriction (TAC) in mouse heart." (PMID 36978846, 2023).
Cerebral (3 papers, 2020 to 2025). "In agreement with its essential functions in mitochondria, Lonp1 KO causes embryonic lethality in mice, and mutations of LONP1 cause a severe genetic disease named CODAS (Cerebral, Ocular, Dental, Auricular, and Skeletal) syndrome." (PMID 40305312, 2025).
lymphoma (3 papers, 2019 to 2023). A malignant (clonal) proliferation of B- lymphocytes or T- lymphocytes which involves the lymph nodes, bone marrow and/or extranodal sites. "As Lonp1 protein levels are increased in malignant lymphoma cells if compared with B cells, and considering that Lonp1 knockdown causes lymphoma cell death, the pharmacological inhibition of Lonp1 by CDDO could represent a promising therapeutic approach for B-cell lymphoma." (PMID 31766211, 2019). "Subsequently, 2-cyano-3,12-dioxooleana-1,9-dien-28-oic acid (CDDO) and its derivatives were found to contribute to lymphoma cell death by downregulating LonP1." (PMID 36362158, 2022).